INS (insulin)
Diseases named in the same sentence as INS in open-access papers (continued):
Sharing a sentence is not in itself a finding about the gene and the disease.
Insulin resistance (continued). "Insulin resistance plays a key role in the pathogenesis of PCOS and hence decreasing circulating insulin levels serves as a therapeutic target in them." (PMID 34268040, 2021). "It has been confirmed that insulin lowers SHBG concentrations in IR generally, and insulin-resistant PCOS specifically." (PMID 34572562, 2021). "Suppression of WAT lipolysis occurs rapidly after the onset of hyperinsulinemia, and the degree of WAT insulin resistance after just several days of HFD feeding is subtle and can be surmounted with high plasma insulin concentrations." (PMID 33411692, 2021). "The protein profiles of insulin sensitive organs, namely, white adipose tissue (WAT), liver, and skeletal muscle were detected in an insulin resistance mouse model via proteomics." (PMID 35116003, 2021). "Regarding the intraperitoneal Glucose Tolerance Test (ipGTT) and the intraperitoneal Insulin Tolerance Test (ipITT), the adoption of a lifelong HFD led to glucose intolerance and insulin resistance, but diet reversion prevented this affect." (PMID 33941835, 2021). "Interestingly, only mice fed the WD display evidence of insulin resistance, with fasting hypoglycemia (120.3 mg/dL) observed as early as 8 weeks after diet initiation and developing a four-fold increase in fasting circulating insulin (4.2 ng/mL) after 24 weeks." (PMID 33946347, 2021). "Supporting this, a previous study have demonstrated alterations of insulin secretion in relation to excess aldosterone levels in animals and in murine islets, as well as plasma aldosterone levels could predict the development of insulin resistance, shown in a previous prospective study." (PMID 34350730, 2021). "In the same way, we also observed a reduction in several proteins involved in insulin signaling in 18-week HFD-fed mice, contributing towards insulin resistance." (PMID 34850865, 2021). "Due to the induction of oxidative stress, group III diabetic rats manifest symptoms of insulin resistance which is evident by the elevated FBG and serum insulin levels accompanied by impaired glucose and insulin tolerances." (PMID 34946771, 2021). "Hematopoietic-specific deletion of APPL1 aggravated HFD-induced glucose intolerance and insulin resistance, as assessed by glucose tolerance test (GTT) and insulin tolerance test (ITT), respectively." (PMID 34789781, 2021). "We compared clinical characteristics consisting of a homeostatic model assessment for insulin resistance (HOMA-IR) and beta cell function (HOMA-β), a quantitative insulin sensitivity check index (QUICKI), and triglyceride glucose (TyG) index." (PMID 34442147, 2021). "In terms of systemic insulin resistance, both caffeine and EGCG significantly reduced the HOMA-IR index and fasting insulin level, although caffeine was better than EGCG at reducing the HOMA-IR index." (PMID 34881283, 2021). "The homeostasis model assessment of insulin resistance (HOMA-IR) and serum insulin levels is usually used to assess the condition of insulin resistance." (PMID 34959901, 2021). "Indeed, since insulin has a direct effect on adipose tissue to promote glucose uptake and TG synthesis and suppress the release of FFA and glycerol into circulation, it is not surprising that adipose insulin resistance is associated with the onset of skeletal and hepatic insulin resistance." (PMID 34069950, 2021). "Based on the reduced blood glucose and insulin levels in Npgl-overexpressing HFD-fed mice at the experimental end point, we propose that NPGL prevents HFD-induced glucose intolerance, insulin resistance, and hyperglycemia in mice." (PMID 33925193, 2021). "The weight loss and combined intervention groups showed significant reductions in levels of: insulin, C-peptide, homeostatic model assessment 2 (HOMA2) insulin resistance (IR), and HOMA2 beta-cell function (β) compared to the control group." (PMID 34578984, 2021).
Insulin resistance (continued). "We also assessed the impact of pioglitazone on cytokine levels, insulin, and inflammatory mechanism in HFCD-induced insulin resistance." (PMID 34037093, 2021). "By the age of 3.5 years, she had normal glucose tolerance and HOMA index 0.6 but markedly elevated stimulated insulin, decreased WBISI 0.44, and acanthosis nigricans, indicative of insulin resistance." (PMID 34177811, 2021). "The iAUC indicates that HFD mice developed insulin resistance (7529 ± 1469 mg/dL) compared to SD mice (13,804 ± 1816 mg/dL) and, interestingly, HFD+E administration was able to induce a partial rescue of insulin sensitivity in mice (10,138 ± 1620 mg/dL)." (PMID 33924725, 2021). "The HAIR-AN syndrome (hyperandrogenism, insulin resistance, and acanthosis nigricans), a subset of PCOS marked by extreme insulin resistance, demonstrates the significance of insulin signaling in PCOS." (PMID 34563259, 2021). "Insulin resistance measured by homeostasis model assessment (HOMA) index and insulin sensitivity using the quantitative sensitivity check index (QUICKI) did not change significantly in both females and males." (PMID 34950736, 2021). "Fasting insulin concentration and the HOMA-IR index are widely accepted measures of insulin resistance and are closely correlated with more precise but laborious measures such as an intravenous glucose-tolerance test or the euglycemic-hyperinsulinemic clamp." (PMID 33804764, 2021). "Insulin-mediated suppression of endogenous glucose production, a reflection of hepatic insulin sensitivity, was markedly better in Slc16a13 knockout mice than wild-type mice, demonstrating attenuation of HFD-induced hepatic insulin resistance." (PMID 34211098, 2021). "Furthermore, the increased insulin release during OGTT, and the higher HOMA-IR values in HFD group compared to control suggest that the observed glucose intolerance may be associated with insulin resistance in HFD group." (PMID 34359921, 2021). "Under these circumstances (e.g., transient insulin resistance during pregnancy), GDM is the result of compromised capacity of pancreatic β‐cells to increase insulin secretion to compensate insulin resistance in insulin‐target tissues." (PMID 33048427, 2020). "Several in vitro studies using the 3T3-L1 adipocyte cell line concluded that JNK plays a role in mediating FFA-induced insulin resistance, and inhibiting JNK has beneficial effects in restoring insulin sensitivity." (PMID 32183037, 2020). "In contrast, insulin resistance markers in women treated with metformin, converged towards those in women without GDM after treatment, with additional improvements in glucose and insulin concentration." (PMID 32240196, 2020). "The FGF21 therapy decreased fasting insulin levels and HOMA-IR, suggesting an improvement in insulin resistance." (PMID 32957703, 2020). "Accordingly, the pan IP6K inhibitor TNP [N2-(m-trifluorobenzyl), N6-(p-nitrobenzyl)purine] ameliorates obesity, insulin resistance and fatty liver in diet induced obese mice by improving Akt and AMPK mediated insulin sensitivity and energy expenditure." (PMID 32204420, 2020). "We used the Matsuda insulin sensitivity index and HOMA-IR to calculate insulin resistance at baseline." (PMID 32757152, 2020). "Studies have shown that intensive insulin therapy can simulate the physiological secretion of human insulin, reduce the burden of pancreatic islet β-cells, and improve the T2DM insulin resistance and islet cell disorders." (PMID 33015194, 2020). "In AT during obesity and insulin resistance, IL6 exposure impairs insulin signalling by interfering with IRS phosphorylation, thus increasing adipocyte lipolysis, which promotes hepatic gluconeogenesis and insulin resistance." (PMID 32785109, 2020). "In this regard, adipose-specific TAZ knockout mice show improvements in insulin sensitivity and glucose metabolism, establishing a potential role for TAZ in promoting insulin resistance." (PMID 31936297, 2020).
Insulin resistance (continued). "Leptin levels correlated with insulin resistance index (IRI) (ρ = 0.484, p < 0.001), BMI (ρ = 0.347, p < 0.001) and insulin concentrations (ρ = 0.336, p < 0.001)." (PMID 32092909, 2020). "In the current study, among the insulin‐related biomarkers, HOMA‐IR (a method to quantify insulin resistance based on the blood concentration of glucose and insulin) showed suggestive evidence (Class III) for an association with a higher risk of CRC." (PMID 32400092, 2020). "Streptozotocin treated mice are the models reflecting insulin secretion failure, and HFD treated mice are the models reflecting insulin resistance." (PMID 32097444, 2020). "Insulin resistance was assessed using HOMA-IR generated from the levels of FPG and insulin in the plasma samples simultaneously withdrawn from mice." (PMID 32824001, 2020). "A well-established marker for insulin resistance is the homeostasis assessment model for insulin resistance (HOMA-IR), calculated from fasting plasma glucose and insulin, which has high specificity and sensitivity in pubertal adolescents with obesity." (PMID 32154197, 2020). "Serum insulin levels in BKO mice were also higher, further supporting that BKO mice showed insulin resistance." (PMID 32245957, 2020). "Since the liver is one of the primary target organs of insulin action, levels of key proteins involved in insulin signaling pathway including InsR, IRS2, and phospho-Akt were detected to investigate insulin resistance in all experimental groups." (PMID 32132984, 2020). "To determine the differences of insulin resistance among cows with different BCS, we measured metabolites related with insulin metabolism." (PMID 32228618, 2020). "A number of animal and clinical studies have shown that BBR improves insulin resistance and obesity-induced metabolic dysregulation, mainly as a result of AMPK activation and inhibition of the inflammatory response in insulin-sensitive tissues." (PMID 33390968, 2020). "CTRP3 expression can decline in insulin resistance, where treatment with glucagon-like peptide-1 (GLP-1) receptor agonist enhances its expression and improves insulin sensitivity." (PMID 32785102, 2020). "Our findings demonstrate that GSNO promotes insulin sensitivity in a sucrose-induced insulin-resistant animal model and further implicates that this antioxidant molecule may act as a potential pharmacological tool for the treatment of insulin resistance in obesity and type 2 diabetes." (PMID 32942712, 2020). "To further unravel the potential mechanisms of TNFR1 inhibition on insulin resistance we analyzed the activation of JNK and its upstream regulator, the MAP-kinase MKK7, since JNK has been identified as negative regulator of insulin signaling." (PMID 32235829, 2020). "The first hypothesis is that UA inhibits insulin-induced endothelial nitric oxide synthase (eNOS) phosphorylation and subsequent nitric oxide (NO) production, thereby contributing to insulin resistance; therefore, using UA lowering agents such as allopurinol improves insulin resistance." (PMID 32549999, 2020). "The glucose stimulated insulin secretion (GSIS) test showed the delayed insulin release and insulin resistance." (PMID 32758178, 2020). "We previously found that LNK inhibited the PI3K-Akt and MAPK-ERK signaling response to insulin, and LNK probably played a role in the development of insulin resistance." (PMID 32911464, 2020). "In insulin-resistant C2C12 cells, both HGSD and RU486 attenuated insulin-resistance to a similar extent." (PMID 32792855, 2020). "Twenty-four women (77.4%) had normal serum insulin levels and seven (22.6%) had raised levels, while a total of 28 (91.3%) women in the SCH group had insulin resistance." (PMID 32550062, 2020). "However, the increased secretion of insulin did not suppress blood glucose and lipid deposition, suggesting that the high-carbohydrate diet might cause symptoms of “insulin resistance” in grass carp." (PMID 32754117, 2020).
Insulin resistance (continued). "In the higher HDL-C tertile, we found modestly higher values as age, TC, and LDL-C and lower BMI, WC, TG, TG/HDL-C, insulin, 2 h insulin and glucose, and HOMA-IR, compatible with diminished insulin resistance." (PMID 32579186, 2020). "Treatment with metformin was considered as a benefit to improve insulin sensitivity, because according to the TTOG performed, the patient presented an insulin test profile that suggested insulin resistance." (PMID 31956423, 2020). "Intriguingly, the improvements of OGTT, plasma insulin and HOMA-IR were observed in HFD-INU group (p < 0.001), indicating that INU effectively attenuated insulin resistance in NAFLD." (PMID 33390939, 2020). "In addition, the effects of HT077 on obesity-induced insulin resistance could be investigated since Nelumbo nucifera and its active constituent nuciferine have been shown to decrease serum insulin levels and homeostasis model assessment for insulin resistance index in HFD-induced obese rodents." (PMID 33158191, 2020). "Homeostasis model of assessment for insulin resistance index (HOMA-IR), insulin sensitivity index (ISI), Area under curve of insulin (AUCINS), and area under curve of blood glucose (AUCBG) were calculated." (PMID 32328036, 2020). "As such, MiR-143-3p knockdown was shown to protect against insulin resistance in patients with metabolic syndrome via targeting of IGF2R and activation of the insulin signaling pathway." (PMID 33207733, 2020). "Intralipid infusion induced insulin resistance both in control and PCOS subjects as shown by the lowering of insulin stimulated glucose disposal rates during the intralipid clamp." (PMID 33101202, 2020). "Interestingly, a reduced SCAT CTSB mRNA expression was associated with increased whole-body insulin resistance (i.e. fasting glucose, insulin and HOMA-IR), independent of adiposity, while an increased SCAT CTSL1 mRNA expression was only associated with adiposity (i.e. BMI and WHR)." (PMID 32486882, 2020). "Indeed, acute or chronic increase in plasma insulin in healthy normoglycemic subjects results in significant decrease in insulin-stimulated glucose disposal, implying that primary hyperinsulinemia may drive insulin resistance." (PMID 32128655, 2020). "ITT and GTT showed that HFD-fed OGT AKI mice were less glucose-tolerant and less insulin-sensitive than WT control mice, demonstrating that OGT overexpression in adipose tissue promotes HFD-induced insulin resistance in mice." (PMID 31924761, 2020). "In accordance, we showed in our full cohort of 72 study participants that increased BMI was positively correlated with serum triglycerides, glucose, insulin, HbA1c and CRP levels, and with insulin resistance (HOMA)." (PMID 32023876, 2020). "To further explore the effect of MNAM on insulin resistance, we demonstrated that MNAM reduces the HOMA-IR index of obese T2DM mice and increases both the QUICKI insulin sensitivity index and the Matsuda index." (PMID 32280711, 2020). "On the other hand, patients may present with slowly progressive insulin deficiency, variable levels of insulin resistance and often do not require insulin treatment for a considerable period after diagnosis-the so-called “latent autoimmune diabetes in adults” (LADA)." (PMID 33292447, 2020). "Insulin resistance in peripheral tissues is a central feature of T2DM as well as gestational diabetes, which inhibits glucose entering into the insulin-dependent cells as adipocytes, skeletal myocytes, and cardiomyocytes." (PMID 32215274, 2020). "In insulin resistance and T2DM, insulin signaling is disrupted resulting in a downregulation of GLUT4 translocation on the surface of the muscle membrane." (PMID 32987623, 2020).
Insulin resistance (continued). "Saroglitazar also reduced fasting insulin levels in DIAMOND mice and was reflected in a significant decrease in insulin resistance as measured by HOMA-IR (homeostatic model Assessment for insulin resistance)." (PMID 32518275, 2020). "Insulin resistance is the typical characteristic of T2DM, a condition in which the targeted cells fail to respond to the hormone insulin stimulation." (PMID 33568989, 2020). "We demonstrated that MNAM can regulate liver gluconeogenesis and insulin signaling pathways in obese T2DM mice, reduce liver tissue lipid deposition, and improve insulin resistance in obese T2DM mice, resulting in reduced fasting blood glucose." (PMID 32280711, 2020). "Next to the key role of ADA in T-cell activity and insulin resistance, it is bound on the cell surface by CD26 protein (DPP-4) that is an important modulator of insulin secretion." (PMID 33053898, 2020). "The homeostatic model assessment of insulin resistance (HOMA-IR), calculated from fasting plasma glucose and insulin level, was assessed as an index of insulin sensitivity at the age of 42–44, 120–122, and 190–192 days." (PMID 33167459, 2020). "Prolonged fasting decreased insulin resistance (HOMA-IR), which was related to an increase in insulin sensitivity (Glucose F = 8.015, p = 0.0243)." (PMID 32435650, 2020). "Across the participants as a whole, median FPG, insulin, HOMA‐IR, HOMA‐β, and Log HOMA‐β were above the normal range, indicating the presence of prediabetes and insulin resistance." (PMID 33102766, 2020). "Although serum insulin levels were similar in the SDT and SD groups, blood glucose levels were significantly higher in the SDT group, suggesting the presence of insulin resistance." (PMID 32405506, 2020). "It has been shown that SOCS1 and SOCS3 are involved in the induction of insulin resistance, and that the ablation of SOCS3 expression in adipose tissue of female mice improves insulin sensitivity to obesity." (PMID 33519913, 2020). "Ferritin was positively correlated with insulin-AUC (r = 0.547, p = 0.008) and TSAT was negatively correlated with waist-hip ratio (r = − 0.385, p = 0.008), insulin (r = − 0.551, p < 0.001), and insulin resistance (HOMA-IR, r = − 0.586, p < 0.001)." (PMID 32821534, 2020). "The analyses of relationships between chemerin, fasting insulin, and HOMA-IR (homeostatic model assessment of insulin resistance) values lead to contradictory results." (PMID 33321877, 2020). "These insulin levels and their corresponding GIR indicated an expected degree of insulin resistance in the diabetic group compared with that of normal subjects, although the studied diabetic group had fair glycaemic control (HbA1c = 6.6 ± 0.3%)." (PMID 32308680, 2020). "As HOMA-IR can more consistently predict type 2 diabetes compared with other insulin resistance indices, we further calculated HOMA-IR based on FPG and insulin levels." (PMID 34026300, 2020). "Homeostasis model assessment‐insulin resistance (HOMA‐IR) has been shown to be useful for the early detection of NAFLD and liver fibrosis, but few studies have investigated the influence of insulin secretory function (ISF) on liver fibrosis in NAFLD." (PMID 33102766, 2020). "The use of strong insulin-sensitizers like DCI and their derivatives could serve as an alternative treatment, based on compounds easily obtained from natural sources, whose use in high doses in humans has proven to be safe and effective in other pathologies caused by insulin resistance." (PMID 32825356, 2020). "Insulin increases NO production via posttranslational modification of eNOS via PI3K/AKT activity; however, this mechanism is suppressed during insulin resistance." (PMID 32819363, 2020). "Although obesity increases risks for insulin resistance, several studies have demonstrated that both obese and non‐obese PCOS patients had impaired insulin signalling." (PMID 32869942, 2020).